CDK2 (cyclin dependent kinase 2)
Diseases named in the same sentence as CDK2 in open-access papers (continued):
Sharing a sentence is not in itself a finding about the gene and the disease.
tumor (continued). "Western blot analysis also demonstrated the same trend, with the expression of Cyclin A1 and CDK2 being downregulated in the tumor tissues of the HSA-372 group of nude mice." (PMID 26673619, 2016). "More importantly, dinaciclib demonstrated in vivo anti-tumor efficacy in multiple NB mouse models via inhibiting CDK2 and CDK9 activity." (PMID 27378523, 2016). "More importantly, dinaciclib significantly inhibited NB tumor growth in two orthotopic mouse models by blocking CDK2 and CDK9 activity and inducing tumor cell death." (PMID 27378523, 2016). "HULC induced tumor proliferation, migration and cell cycle progression by modulating the expression of Cyclin A/D1/E, p-Rb, c-Myc, CDK2/4, and p16/p21/27, which are targets of Skp-1/2 and inhibitors of CDK2/4 and EZH2." (PMID 26894862, 2016). "The protein expression levels of cyclin D1, CDK4, cyclin E, CDK2, and Ki-67, a biological tumor marker that indicates changes in tumor proliferation, were reduced in the shVCP-transfected HCT116 cells, and increased in the lenti-VCP transfected RKO cells." (PMID 27344168, 2016). "The expression of cyclinE was upregulated and Cdk2 was downregulated significantly in NBT compared with tumor tissues." (PMID 25213357, 2015). "The sunitinib-resistant tumour cell response to sorafenib was different from the control cell response, in as much as cdk1 and cdk2 were elevated and p27 was reduced over controls in Caki-1 cells." (PMID 25444514, 2015). "More interestingly, several STAT3-regulated proteins important for tumor cell growth and apoptosis, such as CDK2, cyclin A or caspase 3, exhibited a down-regulated expression and cleaved activation respectively in STAT3-knockdown U266 cells." (PMID 25865044, 2015). "As a major player in mammalian cell cycle progression, CDKN1A inhibits cyclin/cdk2 complexes and plays a crucial role in mediating growth arrest when cells are exposed to DNA damaging agents, implying its tumor suppressive role." (PMID 26582573, 2015). "Since amygdalin strongly modified cdk2 and cyclin A in all tumor cell lines and these proteins regulate entry into the mitotic cycle, the role of these proteins in tumor growth was evaluated by siRNA knock-down." (PMID 25136960, 2014). "Since the most outstanding effects of amygdalin were observed on the cdk2-cyclin A axis, siRNA knock down studies were carried out, revealing a positive correlation between cdk2/cyclin A expression level and tumor growth." (PMID 25136960, 2014). "p21WAF1 is a tumour suppressor gene that can induce disruption of the Cyclin-e/Cdk2 complex and prevent subsequent progression from G1 phase into S phase of the cell cycle." (PMID 25400509, 2014). "This gene is important for G1-S cell cycle control, it binds to and activates the Cdk2, and then accelerates the cell enter into S phase and achieves unrestricted tumor growth." (PMID 25408144, 2014). "The HDAC-inhibitor, VPA, counteracted everolimus resistance in Cakires, evidenced by a significant decrease in tumor growth and cdk2/cyclin A." (PMID 24935000, 2014). "The present investigation also indicates that histone H3 and H4 acetylation diminishes tumor growth, probably by influencing the cell cycle activating proteins cdk2/cyclin A." (PMID 24935000, 2014). "Cdk2's binding partner, Cyclin A, has been correlated with tumor grade and poor disease-specific survival, evidenced by immunohistochemistry and cDNA microarrays." (PMID 25136960, 2014). "The functional relevance of cdk2 and cyclin A in tumor growth was verified by siRNA knock down, revealing significant growth inhibition after cdk2 and cyclin A loss." (PMID 24935000, 2014). "For example, in a previous study, a p27-luciferase-expressing tumor cell was used to monitor Cdk2 activity by in vivo bioluminescence imaging in hollow fibers." (PMID 23301056, 2013).
tumor (continued). "Recent studies showed that SHP1 regulates cell cycle, proliferation and tumor progression by modulating cell cycle machinery through cyclin-dependent kinase 2 (CDK2), p27 and CyclinD1." (PMID 23842094, 2013). "On the other hand, CDK2 inhibitors result in reduced cell proliferation and enhanced apoptosis in vitro and reduced tumor growth in xenografts resistant to trastuzumab." (PMID 22482061, 2012). "The cytoplasmic relocalization of phosphorylated p27 relieves CDK2 from p27-mediated inhibition, thus resulting in cell cycling and tumor-cell proliferation." (PMID 23300741, 2012). "Inhibition of Cdk2 in cultured pre-tumorigenic and tumor cells of both backgrounds resulted in decreased proliferation and evidence of senescence." (PMID 22548705, 2012). "Immunohistochemical staining of tumor sections revealed that the proportions of Ki-67-positive cells and the expression of CDK2 and CDK4 were increased in mice co-injected with 4T1 cells and M2-Mφs." (PMID 22616919, 2012). "Cyclin E suppression mediated by CDK2 inhibition reduced tumor growth among xenografts that were insensitive to TZMB." (PMID 22482061, 2012). "Activation of CDK2 and pERK, and that the bypass of regulatory controls in cell cycle progression and cell apoptosis appear to significantly influence tumor growth and survival." (PMID 22096483, 2011). "metformin's inhibitory effects on tumor cell growth requires sufficient levels of CDKis (p21Waf1/Cip1 or p27Kip1) to bind and inhibit CDK2; b)." (PMID 21483040, 2011). "Among them 13-1-e shows the most promising effects on the zebrafish embryonic growth, the selective inhibition of cyclin E/CDK2 kinase activity, and the prevention of tumor cell proliferation in vitro and tumor size in vivo." (PMID 19194508, 2009). "The compound we identified inhibits zebrafish embryo growth at a specific cell cycle phase, reduces mammalian CDK2 activity as well as tumor cell proliferation in vitro and in vivo." (PMID 19194508, 2009). "Furthermore, CDK2 inhibition has been shown to enhance anti-tumor immunity by increasing the IFN response to endogenous retroviruses." (PMID 41532831, 2026). "Furthermore, CDK2 is crucial for cyclin D1-mediated centrosome overduplication, which impacts to chromosomal instability and supports tumor progression." (PMID 39929880, 2025). "Our findings indicate that Cdk2-/- tumor cells combined anthracyclines trigger a more robust series of immunostimulatory stress pathways than WT cells, including apoptosis stress, endoplasmic reticulum stress, HMGB1 release, and type-1 interferon response, stimulate DCs and T cells infiltration." (PMID 40557162, 2025). "CRISPR-mediated CCNE1 perturbation and patient-derived endometrial xenograft models could clarify the effects of CCNE1 on tumor growth, immune infiltration, and sensitivity to CDK2 or WEE1 inhibitors." (PMID 41331376, 2025). "FAM50A may be a novel prognostic marker for CRC, and may participate in regulating tumor progression by targeting the CyclinA2/CDK2 signal pathway." (PMID 39999107, 2025). "Therefore, there is a critical need to explore the pharmacological complexities of CDK2 inhibitors across different tumor models, considering the distinct roles of CDK2 in driving cell cycle progression." (PMID 39924553, 2025).
tumor (continued). "By simultaneously inhibiting both CDK4/6 and CDK2, this approach maximizes tumor growth inhibition." (PMID 40243688, 2025). "Additionally, we tested expression of CDK2 by IHC in the paired pre‐therapy and post‐therapy tumor samples from three lenvatinib‐resistant ATC patients." (PMID 39716890, 2025). "These phenomena may be attributed to heightened sensitivity to immunogenic cell death, increased ISG expression and PD-L1 expression in tumor cells after CDK2 inhibition." (PMID 40557162, 2025). "In addition, we observed the increase of CDK2 expression in post‐therapy tumor samples from three lenvatinib‐resistant ATC patients." (PMID 39716890, 2025). "CDK2 is implicated not merely in the cellular cycle process, but the inhibition of CDK2 within tumor cells is also instrumental in eliciting anti-neoplastic immune reactions." (PMID 40557162, 2025). "Therefore, AMBRA1 decreased CDK2 expression by inhibiting miR‐1178 expression, which ultimately suppressed tumour growth and metastasis of NSCLC." (PMID 40464146, 2025). "Therefore, we analyzed the difference in immune cell infiltration in the tumor microenvironment between WT tumors and Cdk2-/- tumors after MTX treatment." (PMID 40557162, 2025). "In addition, inducing apoptosis in tumor cells appears to be a primary mechanism behind the anti-tumor effects of brown seaweed polysaccharides, involving factors such as Caspases, Bax, Bcl-2, and CDK-2." (PMID 39057425, 2024). "CDK2 became less active while HGF became more active indicating a switch to a MES-like tumor." (PMID 38766170, 2024). "It has been demonstrated that HuR binds to the 3′ UTR of cyclin A2 and stabilize the mRNA of cyclin A2 in CRC cells in a cell cycle-dependent manner, as cyclin A2, a cofactor of cyclin dependent kinase 2 (CDK-2) enhances tumor cells progression through the S phase." (PMID 38801618, 2024). "Tumours with high nuclear cyclin E1/high nuclear CDK2 have a worse PFS and OS." (PMID 38612869, 2024). "Tumours with high nuclear cyclin E1/high nuclear CDK2 also had a worse PFS and OS." (PMID 38612869, 2024). "In addition, there is also an opportunity for synthetic lethality, particularly in CCNE1-amplified tumours that are addicted to CDK2-dependent pathways." (PMID 38732271, 2024). "Furthermore, PTEN’s tumor suppressor role extends to cell cycle regulation, where it fosters p27Kip1 binding to the CyclinE/cyclin-dependent kinase 2 (CDK2) complex, inhibiting CDK2 kinase activity." (PMID 39298504, 2024). "Interestingly, the gene that showed the lowest expression in high-CDK2 tumours was the non-coding 7SK RNA/RF00100, which has been implicated in the inhibition of cell proliferation." (PMID 38732271, 2024). "For CDK2, 1% of tumours harboured genetic alterations (9 amplification, 1 missense mutation)." (PMID 38612869, 2024). "Meanwhile, Western blot analysis demonstrated that AS-TP downregulated the expression of cyclin A and CDK2, which indicated that AS-TP suppressed tumor proliferation by modulating the expression in MDA-MB-231 cells of cyclin and cyclin-dependent kinase during DNA replication." (PMID 39054545, 2024). "The abnormal stoichiometry of centrioles described after CDK2 inhibition could confer resistant or persistent tumor cells." (PMID 38031910, 2023). "In vitro experiments revealed that FOXD1 bound to the p21 promoter and inhibited its transcription, which blocked the cyclin dependent kinase 2 (CDK2)/retinoblastoma (Rb) signaling pathway, thus preventing senescence and accelerating proliferation of tumor cells." (PMID 37563111, 2023).
tumor (continued). "Further, correlation analysis revealed the positive correlation between MPGSs and CDK2 kinase activity was observed only in GBMs, emphasized variability in CDK2 activity strongly associated the tumor proliferation rates in GBMs but not in LGGs." (PMID 36720864, 2023). "Knocking down CDK1, CDK2, and Cyclin A significantly reduced the tumor cell number (right)." (PMID 37835543, 2023). "Alternatively, changes in CDK2 levels may be very transient and/or restricted to a small population of actively dividing tumor cells and thus difficult to capture." (PMID 37936247, 2023). "Collectively, these data suggested that FOXD1 may promote tumor malignancy in HNSCC by inducing the p21/CDK2/Rb pathway." (PMID 37563111, 2023). "In addition, we found that FOXD1 directly bound to the promoter of p21 and inhibited its transcription, which blocked the CDK2/Rb signaling pathway, thereby preventing the senescence of tumor cells and accelerating tumor cell proliferation." (PMID 37563111, 2023). "Amygdalin has also been found to inhibit tumor development via downregulation of cdk2 and cyclin." (PMID 37762572, 2023). "In fact, in vitro studies have demonstrated the anti-tumour effect of 800 μM melatonin for 72 h, as it is able to inhibit tumour growth through the downregulation of cyclin-dependent kinases 2 and 4 (CDK2 and CDK4) in ovarian cancer cell lines PA-1 and OVCAR-429." (PMID 36670948, 2022). "CCNA2 could activate CDK2 during the S phase, allowing the cell cycle to proceed normally, and it also could be recognized by high-avidity T-cells to perform function in tumor immunity." (PMID 36325324, 2022). "Because inhibition of CDK2, 4 and 6 exhibits potent antitumor activity, increased regulation of proteins involved in the formation of their mediated checkpoints is expected to increase tumor cell survival." (PMID 36142752, 2022). "In addition, tumor development is usually accompanied by the up-regulation of cyclin E, which has a high affinity toward CDK2." (PMID 35699421, 2022). "The cyclin E/CDK2 axis is known to enhance tumor growth in addition to CDK4/6 function, which subsequently drives cell cycle progression and could potentially bypass CDK4/6 inhibition for cell cycle transition." (PMID 35884422, 2022). "Furthermore, SP1 participated in tumor progression via regulating multiple downstream genes, such as vimentin, cadherin, E-cadherin, and CDK2." (PMID 33345272, 2021). "Several lines of evidence suggest the use of novel therapy, such as CAPTEM, PRRT, EVE, immunotherapy, EGFR inhibitors, CDK2 inhibitors, and RA, could be valuable strategies for long-term tumor control." (PMID 33841328, 2021). "Many molecules involved in tumor classical signaling pathways were related to CDK2 expression." (PMID 34409029, 2021). "CDK2 is a main cell cycle protein which could promote the transition from G1 to S phase, thereby promoting the proliferation of tumor cells and the development of tumors." (PMID 33460401, 2021). "Furthermore, co-therapy with paclitaxel and CDK2 inhibitor showed synergistic effects in tumor suppression." (PMID 33541412, 2021). "Most important, CDK5 is directly involved in the degradation of the cell cycle inhibitor p21 and can enhance CDK2 activity, which might further promote tumor cell growth." (PMID 35002699, 2021). "The IC50 level of 89 anti-tumor drugs were related to the expression of CDK2." (PMID 34409029, 2021). "Because of the correlation of CDK2 and various immune cells, CDK2 may be involved in tumor regulation of immune infiltration." (PMID 34409029, 2021). "Here are the top 20 anti-tumor drug resistance studies related to CDK2." (PMID 34409029, 2021).
tumor (continued). "Thus, cyclin E1/CDK2 activation coupled with tumor suppressor FBW7 loss can promote CIN and tumor progression through reducing CENP-A’s centromeric localization, leading to centromere dysfunction." (PMID 32708729, 2020). "Hyperphosphorylation of CENP-A Ser18 by cyclinE1/CDK2 reduced its centromeric localization, increased levels of lagging chromosomes, chromosomal bridges, and micronuclei formation, and even promoted anchorage-independent growth and xenograft tumor formation." (PMID 32708729, 2020). "The cyclin dependent kinase CDK2 is the target of tumor treatment." (PMID 32963562, 2020). "Previous reports also showed that CCNE2 could drive tumour cell proliferation by activating its kinase partner CDK2,47, 48 but whether CCNE2 could directly regulate CDK4 was still unclear or CCNE2 affect the expression of CDK4 via an indirect manner." (PMID 32141702, 2020). "TSPO was identified as a key target gene of CDK2, and CDK2 may be involved in tumor progression via the regulation of the interaction of TSPO and CDK1." (PMID 33066460, 2020). "In addition, the abundance of NF90-Ser382 phosphorylation is consistent with CDK2 protein levels throughout the cell cycle, suggesting that NF90 is under tight regulation by CDK2 during tumor cell proliferation." (PMID 32123579, 2020). "In view of the important role of cell cycle arrest in tumor cell growth inhibition, the expression of several cell cycle-related proteins was investigated and RC influences the expression of CDK2 and CDK4, which suggests the feasibility of cell cycle arrest in G0/G1 and G2/M." (PMID 31817918, 2019). "The levels of CDK2 and cyclin A in the tumor tissues were detected by western blotting." (PMID 31231581, 2019). "In addition, we predicted and verified that the effect of TSG101 on the growth of tumor was related to elevated c-myc protein levels, accompanied by up-regulated cyclin E1/cyclin-dependent kinase 2 (CDK2) complex." (PMID 30675171, 2019). "The risk score was calculated as follows: risk score = 3.13 × (Notch4) ± 1.52 × (p-PKCα/β2) + 0.74 × (XIAP) + 0.58 × (CDK2) + 0.77 × (Akt1) + 0.74 × (TNM stage) + 1.20 × (vascular/lymphatic invasion) + 0.97 × (tumor size) + 0.61 × (age) + 0.58 × (histologic differentiation)." (PMID 31399040, 2019). "Therefore, CDK5 directly targets nuclear p21CIP1 protein and activates CDK2, which represents an important role in the regulation of the cell cycle in the G1-S phase, and therefore, tumor growth is promoted." (PMID 31395805, 2019). "Downregulation of NKG2D receptor expression in tumor cells can increase the expression of cyclin E and cyclin-dependent kinase 2, reduce the expression of p21, and increase the number of tumor cells in G1 and S phases, leading to inhibition of tumor cell proliferation." (PMID 30813924, 2019). "Both CCNE2 and CDK2 expression remained high and unchanged after doxorubicin treatment, and it has been described that overexpression and interaction of these two genes is related with tamoxifen-resistance mechanisms in breast cancer." (PMID 30926829, 2019). "Therefore, it is possible that parkin KO reduced p21 ubiquitination and degradation, leading to increased p21/CDK2 or p21/PCNA complex association, which ultimately resulted in the inhibition of tumor growth through cell cycle arrest." (PMID 31112565, 2019). "Furthermore, elevation of RB and p27 and reduction of cyclin A, cyclin B, and CDK2 in selinexor treated tumors confirms that selinexor impairs tumor cell proliferation in vivo." (PMID 30349650, 2018). "Similarly, the mean scores of CDK2 in tumor tissues and adjacent normal tissues were 7.018 ± 0.6516 and 3.644 ± 0.5090, respectively (P < 0.0001, Wilcoxon signed rank test)." (PMID 30237499, 2018). "Because the effects of miR-3140 on in vitro tumor cell growth were much greater than those of si-CDK2 and si-EGFR, concurrent downregulation of additional target genes may be necessary for the induction of miR-3140-mediated inhibition of tumor cell growth." (PMID 29540837, 2018).